CD44 (CD44 molecule (IN blood group))
Diseases named in the same sentence as CD44 in open-access papers (continued):
Sharing a sentence is not in itself a finding about the gene and the disease.
tumor (continued). "Specifically, the use of drug-containing cubosomes engineered to target CD44+ tumor cells did succeed therapeutically in several cancer cell lines in vitro, with continuing research to evaluate the use of CD44 as a therapeutic target." (PMID 36831112, 2023). "In detail, compared to the saline group, CyOA NPs + L treatment reduced the proportion of CD133+ tumor cells by 24.5%, side population cells by 94.1%, and CD44+CD24− tumor cells by 30.3%." (PMID 37680304, 2023). "Chitosan–hyaluronan NPs were proposed as a nanocarrier for VBL-targeted delivery to CD44-transmembrane receptors overexpressed in tumor cells." (PMID 36839824, 2023). "Herein, hyaluronic acid (HA) was hydrophobically modified to serve as a carrier for binding to cluster determinant 44 (CD44) overexpressed on tumor cell surfaces." (PMID 37600308, 2023). "To delineate the inter-tumor heterogeneity of CD44, we studied it among four molecular sub-classes according to the VERHAAK_2017 classification scheme." (PMID 36776876, 2023). "Evidence has shown that the tumorsphere- and colony-forming ability of tumor cells is regulated by the stemness of tumor cells and the enhanced stemness of CSCs is often closely related to the abnormal expression of CD44, CD24, CD133, and Lgr5." (PMID 37005676, 2023). "We also compared the differences in expression levels of TEX marker genes (HAVCR2, TIGIT, CTLA4, LAG3, and PD1) and the putative tumor stem cell marker genes (CD44 and PROM1) between high and low TEXSRGs-score groups in clinical tumor samples using qRT-PCR." (PMID 37957420, 2023). "In different cancers, the classic features of tumour-inducing cells have been shown in animal experiments using CD44-positive malignant cells." (PMID 37108193, 2023). "Tumor-derived cells, however, express CD44 in a high-affinity state that can promote the binding and internalization of HA." (PMID 36839696, 2023). "Low passage cytokeratin+, aneuploid MPE tumor cells evidenced a high degree of EMT as documented by surface expression of CD90, CD44, and loss of surface expression of EpCAM." (PMID 37063842, 2023). "Second, specifically expressed proteins on platelet membranes can recognize receptors on the surface of tumor cells, thus enhancing the active targeting ability of NPs, such as P‐selectin (receptor) and CD44 (ligand)." (PMID 36925700, 2023). "Recently, HA-CD44 interactions have been utilized in HA-conjugated nanoparticles to improve anticancer efficacy via enhanced internalization of nanoparticles in CD44-overexpressed tumor cells." (PMID 37627173, 2023). "Cell adhesion molecule CD44, known as one of the most common tumor markers, is overexpressed in GBM and is presented on the surface of GBM-EVs." (PMID 36960410, 2023). "Positive expression for CD44, a typical tumor marker strongly expressed in FLC53,54, was detected in all mutants -but not in wild type organoids- and again more strongly in the double mutant." (PMID 37137901, 2023). "Using these data, we elucidate how CD44 can participate in the generation of tumor recurrence in GBM." (PMID 37835592, 2023). "With special regard to a tumor stem cell-like phenotype (CD24low, CD44high) and the potential to metastasize (represented by a CD44+ phenotype), CD24 and CD44 were included in the analysis." (PMID 37174080, 2023). "We found that several protein biomarkers, most notably panCK, IDO1, CD44, and Ki-67, were expressed at higher levels in responders’ tumor compartments; however, in the stroma, SMA, Fibronectin, CD4, and CD27 were the most differentially expressed." (PMID 37153589, 2023). "TGF-β is a well-known EMT-inducer via alternative splicing of CD44, forming an isoform capable of migration, invasion, and tumor initiation." (PMID 37190236, 2023). "We also evaluated the cell surface expression of CD47 and CD44 molecules in response to the NaHCO3 and anti-PD-L1 treatments, in a single cell suspension generated from the 4T1-Luc tumor tissues." (PMID 37894298, 2023).
tumor (continued). "CD44 interacts with various extracellular matrix (ECM) constituents within the tumor microenvironment, with hyaluronic acid (HA) being the primary ligand for CD44." (PMID 37509716, 2023). "These cells were first discovered as CD44 + CD24 + ESA + cells with the ability to develop tumors at a significantly higher frequency than the bulk tumor." (PMID 37173787, 2023). "Similar results were observed in the xenograft mice model, wherein the mice injected with 786-O control cells developed tumors, whereas CD44 overexpression substantially amplified the tumor proliferation rate." (PMID 37509716, 2023). "FKA inhibited the expression of stem cell markers (Nanog, Oct4, CD44), neddylation of Ubc12 and the expression of c-Myc in both prostaspheres and tumor tissues." (PMID 37373500, 2023). "The combination of CD4+ T cell depletion and PD-L1 blockade significantly increased the proportion of CD44+CD69+CD8+ T cells in CT26 tumor tissues." (PMID 36969495, 2023). "FUT9-mediated hyperfucosylation also triggered Sox2, ALDH, and CD44 expression and tumor sphere formation." (PMID 37298124, 2023). "tumor and ascitic fluid were positive for CD44, and weak expression of CAFs (PDGFRα, FAP) was observed." (PMID 37958844, 2023). "Compared with conventional glioma spheroid suspensions, GBM organoids grow in high HA content hydrogels and upregulate expression of CD44, which is an HA‐binding cell surface receptor and tumor stem cell marker." (PMID 37081739, 2023). "Similar to our cell lines, the mouth, hypopharynx and oropharynx tumor cell lines also show a high percentage of CD44-positive cells." (PMID 36864434, 2023). "Tumor sections were stained with CSC biomarkers (CD44, c-Myc, EpCAM) and macrophage biomarkers (F4/80, CD68)." (PMID 37553567, 2023). "Differentiated cells at days 26 and 30, characterized by negligible expression levels of TIMP1, MMP9 and CD44, were unable to induce tumor growth." (PMID 36906579, 2023). "Our previous studies reported that higher expression of CD44 in the tumor periphery compared to the tumor core in GBM correlates with tumor invasiveness as defined from MRI." (PMID 37760811, 2023). "IHC staining of CD44 in tumors from mice co-injected with tumor cells and shNC or shSpry2 fibroblasts showed enhanced CD44 expression in shSpry2 groups." (PMID 37507768, 2023). "This study uncovered the regulation mechanism and its molecular basis for CD44-HA affinity under diverse mechano-microenvironments and provided a new insight into CD44-HA interaction-mediated cell inflammatory responses and tumor development." (PMID 36768572, 2023). "Breast tumor CSCs have an increased tumor initiation potential and express various cell surface markers (e.g., low levels of CD24 and high levels of CD44) compared to other tumor cells." (PMID 37372954, 2023). "Some of the transcripts were revealed in CD90 + /CD44 + positive mesenchymal stromal cells within the tumor, which are known to change their phenotype into CAF-myofibroblasts." (PMID 36635266, 2023). "All these modifications hinder the CD44–HA bond and block the signaling events involved in the biology of tumor cells, from survival to metastasis." (PMID 37107200, 2023). "It is possible that interfering with CD44 function later in life will enable identification of additional tumor-relevant CD44 properties." (PMID 37174657, 2023). "Inhibition of cancer stem cell self‐renewal through reduced expression of STAT1 and CD44 in tumour tissues incubated with EV‐encapsulated napabucasin." (PMID 37294158, 2023). "Cluster of differentiation 44 (CD44) has been investigated as a cancer stem cell (CSC) marker as it plays critical roles in tumor malignant progression." (PMID 37189717, 2023). "CD44 has a high level of expression on bulk tumor cells and CICs, while it has a low level of expression in healthy tissue and differentiated breast tissue, according to the findings." (PMID 36289579, 2023).
tumor (continued). "Taken together, these results suggest that HABN administered IV is taken up by CD44-expressing tumor cells and TAMCs, in particular CD206highMHCIIlow M2-like macrophages." (PMID 37553327, 2023). "The TGF-β pathway induces EMT via alternative splicing of CD44, leading to increased migration, invasion, and tumor initiation." (PMID 37190236, 2023). "Aldefluor positivity has been found to label and detect CSCs in their associated tumor tissue slides when paired with additional unique stem cell surface markers such as CD133+ and CD24 − CD44+." (PMID 36675306, 2023). "Tumor-infiltrating OT-I T cells treated with OE-S-2HG expressed more CD44+/CD62L+ (TCM) than OE-R-2HG- and vehicle-treated cells." (PMID 37632752, 2023). "Animal studies demonstrated that injections of CPE were beneficial in chemotherapy-resistant CD44+ OCSC tumours." (PMID 38201468, 2023). "Osteopontin (OPN)-CD44 signaling plays an important role in promoting tumor progression and metastasis." (PMID 38067149, 2023). "It has been reported that GC cells with tumor stemness characteristics of GCSCs express more CD44 protein on their surface and change their cell morphology to a spherical shape after being cultured in special media." (PMID 37980488, 2023). "On the same note, research in modulating the levels of HA and CD44 and their interactions is considered necessary to disrupt the signaling pathways that favor tumor progression and reduce cancer resistance to therapy." (PMID 37107200, 2023). "The effects of CD44 on tumor cell invasion, proliferation, and progression depend on the specificity of the interactions between CD44 and each ligand." (PMID 37835592, 2023). "The HA receptor CD44 is overexpressed by many tumor cells, and the specific binding of HA to CD44 can increase tumor site aggregation and achieve accurate targeting of certain cancer cells." (PMID 36944946, 2023). "CD44 was first identified as a hyaluronan-binding protein and has been reported both as a tumor suppressor and tumor promoter (reviewed in 41,42)." (PMID 37056934, 2023). "CD44 is a recognized tumor stem cell marker molecule, and its increased expression predicts a malignant transformation change of GES-1 cells under continuous stimulation of Cag A+H." (PMID 36918410, 2023). "Several known stem markers, including the EPCAM, MUC1 and CD44 signatures, promote transformation and tumour progression." (PMID 36661191, 2023). "Over the last decade, CD44 has emerged as a prominent marker for CSCs in various types of cancer and, hence, it provides valuable insights into tumor initiation, progression, and therapy resistance." (PMID 37958796, 2023). "In particular, the authors identified CD44 as an important target of ERK1/2 in the promotion of tumor aggressiveness." (PMID 37047552, 2023). "In vivo therapeutic administration of miR-34a and PTX through systemic delivery also led to delayed tumor growth in a B16F10-CD44+ tumor model by inhibiting CD44 and inducing apoptosis in B16F10-CD44+ cells." (PMID 37104009, 2023). "In summary, this analysis reveals that different tumor-resident cell types such as cancer cells, fibroblasts, CD44 progenitor-like cells and infiltrated macrophages were preserved in these tumoroids." (PMID 37736770, 2023). "We also observed higher frequency of activated CD69+ CD44+ CD8+ splenic T cells in tumor-bearing mice treated with the combination of 5AZADC and ADU-S100 compared to those treated with either single agent." (PMID 36949064, 2023). "Since HNSCC is revealed as the second highest CD44-expressing tumor in the Pan-Cancer Atlas, we examined the reactivity of C44Mab-18 and C44Mab-46 in immunohistochemical analyses using FFPE sections of OSCC tissue array." (PMID 37504249, 2023). "Targeting CD44-positive CSCs not only aims to eliminate the cells responsible for tumor growth and recurrence, but also disrupts the microenvironment and signalling networks that support CSC maintenance and therapy resistance." (PMID 37958796, 2023).
tumor (continued). "The same study also performed in vitro and in vivo investigations that showed that CD44 promoted PCa cell migration, invasion, and tumor initiation." (PMID 37190236, 2023). "In research, CD44+CD24 BCSCs with significant tumorigenic potential were found using serum-free suspension culture thanks to their elevated expression of tumor stem cell markers such ALDH1A1, C-Myc, OCT4, NANOG, KLF 4, and SOX2." (PMID 37880659, 2023). "Meanwhile, the corresponding receptors (integrin αVβ8, syndecan 1 and 4, and CD44) are actively expressed in tumor cells." (PMID 37479733, 2023). "CD44 has been known as a cancer stem cell marker and plays tumor promotion and drug resistance roles in various cancers." (PMID 37218897, 2023). "Among them, recent studies suggest that CD44 plays a critical role in tumor progression through its cancer-initiating and metastasis-promoting properties." (PMID 36835416, 2023). "In the review, one can find detailed information about the engagement of CD44 exons v6 and v3 in the maintenance of CSCs and tumor progression." (PMID 38106992, 2023). "Targeting CD44, miR-145 also exerts tumor-suppressive effects, attenuating EMT responses and reducing chemotherapy resistance." (PMID 38455361, 2023). "In line with that study, we also found that patients overexpressing CD44 more frequently had a high-grade tumor than patients with low CD44 expression." (PMID 36831554, 2023). "In terms of specific L/R pairs, based on the spatial transcriptome expression assessment, stress-like tumor cells were likely to interact with CD44+ IgG1 PCs by secreting LAMB3." (PMID 37138324, 2023). "As for the tumor compartment, the CD44 expression in the tumor cells serves as a novel prognostic factor for extended PFS and OS under anti‐PD‐1 treatment." (PMID 38045830, 2023). "CD44 was stained in the membrane of cancer cells, and its expression correlated with the tumor grade." (PMID 37108495, 2023). "These CD44-positive CSCs possess a higher capacity for self-renewal, tumor initiation, and metastatic potential than their CD44-negative counterparts." (PMID 37958796, 2023). "IF staining indicated that CD44-positive cells are Hmga2+ and Spc−, supporting the idea of using CD44 to subset tumor organoid cells." (PMID 36993454, 2023). "The elevation of HIF‐2α in hypoxic tumour cells increases the number of CD44+/CD24− MDA‐MB‐231 cells via the modulation of the PI3K/AKT/mTOR axis." (PMID 37156724, 2023). "Aberrant expression and dysregulation of CD44 contribute to tumor initiation, progression, and metastasis development." (PMID 36831554, 2023). "The combination of the CD44+ and CD54+ markers has been used for the identification of CSCs in GC since both biomarkers are associated with metastasis, tumor recurrence, and mortality." (PMID 36737794, 2023). "On the one hand, micellar drugs can selectively target at tumor site through the tumor surface receptor CD44." (PMID 37600308, 2023). "For instance, mutation or deletion of the ICD results in the aberrant localization of CD44 within cellular membranes, an inability to bind HA, and impaired HA-mediated cell migration and tumor development." (PMID 37894408, 2023). "Cluster of differentiation 44 (CD44) promotes tumor progression through the recruitment of growth factors and the acquisition of stemness, invasiveness, and drug resistance." (PMID 37176118, 2023). "One well-known proteoglycan is hyaluronan (HA), which acts with CD44 to enhance the growth and migration of tumour cells." (PMID 38085380, 2023). "The transmembrane glycoprotein CD44 is a representative molecular marker for BC stem cells and regulates the adaptive plasticity of tumour cells." (PMID 36127291, 2023). "By interacting with downstream pathways, CD44 has been found to influence stemness and migration in various tumor cell types." (PMID 38455361, 2023).
tumor (continued). "This idea is further supported by recent studies indicating that CD44 enables invasive tumour cells to produce functional invadopodia by promoting the phosphorylation of cortactin and recruiting MT1-MMP." (PMID 37596406, 2023). "We also quantitatively evaluated GBM invasion using 5-aminolevulinic acid (5-ALA) spectroscopy to investigate the relationship between CD44 expression and tumor invasiveness as evaluated by intraoperative 5-ALA intensity." (PMID 37760811, 2023). "GSC are also responsible for tumor metastasis and therapy resistance, which makes CD44 and CD133 important protein markers." (PMID 36960410, 2023). "Consistent with that, the two matching pairs of primary and metastatic tumours, when investigated for their CD44 expression, showed a reduced expression in the matching primary compared with their metastatic counterparts." (PMID 37174052, 2023). "We then determined the expression of tumor stemness markers CD44 and CD133 in ESCC by immunohistochemistry." (PMID 37607071, 2023). "CD44 has already been extensively described as a suitable antigen for tumor targeting since it is overexpressed in a plethora of cancers as lung, prostate, colon, ovarian and others." (PMID 37287910, 2023). "siRNA-GOx/GNR@HA NPs showed the potential to lessen harm to CD44-negative normal cells by targeting CD44-overexpressing cancer cells, hence enhancing tumor formation and penetrating capacity." (PMID 37928851, 2023). "Versican can promote tumor cell invasion and metastasis by activating NF-κB signaling and upregulating the hyaluronic acid receptor CD44, receptor for HA mediated motility(RHAMM), and matrix metalloproteinase 9 (MMP9)." (PMID 37259101, 2023). "Enrichment with CSCs in the tumor spheres was confirmed by an increase in the CSC markers CD44, Nanog, EpCAM, and OCT4." (PMID 37300334, 2023). "In the present study, we demonstrated that GBMs expressing CD44 much higher in the tumor periphery than in the tumor core (as represented by a higher P/C ratio) were most strongly associated with HI-type GBM." (PMID 37760811, 2023). "Further analysis of the CCL5/Sp1/CD44 axis in EpCAM+ cells revealed that this signaling pathway was more activated in advanced tumor stages, which was consistent with the protein analysis." (PMID 37553567, 2023). "The effective tumor growth inhibition through CD44 targeting in the MDA-MB-231 tumor xenograft mouse model was demonstrated." (PMID 37376284, 2023). "MMPs can lead to the shedding of CD44 from the cell surface, while soluble CD44 antagonizes CD44-mediated cellular binding to HA and can modulate or inhibit tumor development and tumor cell migration." (PMID 37762403, 2023). "In our study, elevated CD44 expression correlated with more aggressive tumor behavior and poor prognostic features, suggesting its role as a novel prognostic marker and potential therapeutic target for mCRC patients." (PMID 36831554, 2023). "In Hepa1-6 implanted tumor-bearing model, anti-Spp1 monoclonal antibody (mAb), anti-Cd44 mAb, or anti-Pd-1 mAb alone significantly inhibited the growth of tumors." (PMID 37336873, 2023). "Concordantly, CD44 knockdown resulted in diminished stemness and migration of GC tumor cells, confirming the necessity of CD44 in CSC tumorigenesis." (PMID 38455361, 2023). "The other network included products of genes associated with tumour growth and cell proliferation (FN1, VEGFA), tumour progression and metastasis (CD44, ITGA2) and immune inhibition (NT5E)." (PMID 36649303, 2023). "Macrophage-secreted OPN binds to CD44 on the tumor cells and promotes tumor invasion and clonal growth." (PMID 36980197, 2023). "Taken together, these results show the importance of HABN-mediated delivery of SC144, modulation of macrophages, and CD44 expression among tumor cells for the observed anti-tumor efficacy of SC144@HABN." (PMID 37553327, 2023). "Conversely, lower expression of CD44 in the tumor periphery corresponded with low invasive-type GBM and longer survival." (PMID 37760811, 2023).